HIF1A (hypoxia inducible factor 1 subunit alpha)
Diseases named in the same sentence as HIF1A in open-access papers (continued):
Sharing a sentence is not in itself a finding about the gene and the disease.
cancer (continued). "HIF-1α has been verified aberrantly up-regulated in HCC tissues after TACE by several studies, and exerted the angiogenic effect through mediating pro-angiogenic factors including VEGF, PDGF and PLGF, which ultimately promoted the growth and metastases of cancer cells after TACE42." (PMID 31942180, 2020). "Intriguingly, compared to longer incubation period, 24 h had the highest HIF-1α protein expression, while 48 h had the highest HIF-1α responsive luciferase activity, indicating that cancer cells might constantly be adapted to their metabolic stress microenvironment." (PMID 32308748, 2020). "As HIF-1α could transcriptionally upregulate glycolytic genes and ATF4 activates the expression of amino acid transporters, EPB41L4A-AS1 eventually inhibits glycolysis and glutaminolysis in cancer cells." (PMID 32174794, 2020). "Since several reports have shown that TNF-α likely regulates glucose metabolism in cancer cells without HIF-1α stabilization, the TNF-α signaling pathway might be involved in the induction of aerobic glycolysis in fibroblasts." (PMID 32555715, 2020). "HIF-1α interacts with several growth factors and cytokines, such as VEGF, insulin-like growth factors (IGFs), fibroblast growth factors (FGFs), and epidermal growth factor; the expression of these molecules on cancer cells can further enhance cancer cell proliferation and metastasis." (PMID 32793401, 2020). "The Western blotting also showed that the expression of HIF-1α in lymph node metastasis was higher than that in in-situ cancer tissues, but the difference was not statistically significant, which may be related to the small number of samples." (PMID 32093760, 2020). "Thereafter, we provide novel mechanistic evidence on the hypoxia-prompted liaison between the HIF-1α/GPER signaling and the IL-1β/IL1R1 axis, toward a metastatic gene expression profile of TNBC cells and the engagement of CAFs in facilitating invasive cancer features." (PMID 32778144, 2020). "However, as it is still unknown how activated HSC induced HIF-1α expression in cancer cell, further studies on the relationship of HSC and HIF-1α are required." (PMID 32895059, 2020). "Various studies showed that sorafenib could stabilize HIF-1α expression under hypoxia and increase the expression of HIF-1α targets like MDR1, GLUT-1, VEGF and miRNAs (e.g. miR-210), and the whole progress played vital roles in cancer biology." (PMID 33280610, 2020). "Even though cancer cells use multiple metabolic methods to subvert immune cells from their fundamental role (lactate; IDO, HIF1-α, and probably others), targeting these metabolic pathways together with immune checkpoint inhibitors might, in some settings, improve the clinical response." (PMID 30708988, 2019). "Under normoxia, mitochondrial metabolism in cancer cells may be favored because mTOR triggers mitochondrial biogenesis through TFAM and PGC1-α activation; in addition, mTOR may upregulate glycolysis through HIF-1α activation." (PMID 31600993, 2019). "Previously, we demonstrated that HIF1α-mediated activation of glycolysis had a beneficial effect for the synthesis of ATP under severely hypoxic conditions in directing TH9 cell differentiation in cancer during severe hypoxia or in noncancer T cells." (PMID 31744227, 2019). "YAP and HIF-1α can be detected in CD133− cancer cells with or without rhHMGB1 treatment." (PMID 31558702, 2019). "Interestingly, depletion of ACADL, but not ACADM, by HIF-1α promotes the progression of cancer cells, potentially by mediating the accumulation of unsaturated FAs." (PMID 31092908, 2019). "The effects of HIF-1α SNPs on the prognosis with cancers are not uniform." (PMID 30678691, 2019). "Furthermore, Dichloroacetate, which can restore mitochondrial function, has proven its effectiveness in experimental models of cancer and PAH through the enhancement of glucose oxidation (GO) and the attenuation of mitochondria-induced hypoxia-inducible factor 1α (HIF-1α) signaling." (PMID 31083380, 2019).
cancer (continued). "To gain more insights in the mechanism that regulates HIF‐1A levels in these cancer cells, we cultured Suit‐2 in the soft (1 kPa) and stiff (25 kPa) PAA matrices under non‐hypoxic conditions and observed that stiff substrates promoted transcriptional upregulation of HIF‐1A." (PMID 30538116, 2019). "In addition, inhibition of ERK-mediated phosphorylation of HIF-1α by transduced recombinant HIF-1α-derived peptides abolished induction of lipin-1 expression, reduced lipid droplet accumulation and triggered apoptosis in cancer cells grown under hypoxia." (PMID 30832409, 2019). "Since in, cancer cells, AKT/PKB-mediated inactivating phosphorylation of GSK3β contributes to the cytoplasmic stabilization of HIF-1α as well, one can speculate if an APELIN-AKT/PKB-HIF-1α axis forms a feed-forward regulatory loop in hypoxic bone marrow-derived mesenchymal stromal cells." (PMID 31687031, 2019). "A main metabolic phenotype observed in cancer cells is driven by the Warburg effect, which consists in the shift from ATP generation through OXPHOS to ATP generation through glycolysis, even in the presence of oxygen, being the transcription factor HIF-1α one of its major drivers." (PMID 31121959, 2019). "Therefore, the higher levels of HIF-1α in cancer cells regardless of normoxia or hypoxia correlate with increased levels of glycolytic proteins." (PMID 31600993, 2019). "The role of TGF-β in upregulating the expression of CD73 on cancer cells has been well-documented, and its effects on the expression of CD73/CD39 on myeloid-derived suppressor cells were shown to occur by phosphorylation and activation of mTOR and HIF-1α, respectively." (PMID 31396523, 2019). "In conclusion, unlike the other cancers in which HIF-1α gene SNPs were demonstrated to be associated with the outcome, OCCC prognosis may not be affected by HIF-1α gene SNPs." (PMID 30678691, 2019). "In addition, miR-186 has been reported to have anti-proliferative roles in some cancers; in GC, miR-186 suppresses cell proliferation by negatively regulating HIF-1α and consequently affects downstream HIF-1α target genes, including PD-L1, hexokinase 2, and PFKP." (PMID 31817259, 2019). "Besides, ROS may induce the expression of transcription factors such as Snail and HIF-1α, leading to epithelial to mesenchymal transition (EMT), an aggressive behavior favoring cancer metastasis and involved in drug resistance." (PMID 31583051, 2019). "Thus, it was proposed that cancer cells may benefit from the downregulation of TTP, which subsequently increases HIF-1α expression and assists with the adaptation of cancer cells to hypoxia." (PMID 30380668, 2018). "Notably, highly metabolically active cancer cells release reactive oxygen species, which, in turn, induce oxidative stress in the adjacent fibroblasts and activate HIF1, through the stabilization of HIF1α subunit, and NF‐kB." (PMID 29280568, 2018). "Furthermore, this platform allows for real-time characterization of dormant cancer cells that has not been practical with hypoxic chambers due to the extremely short half-life of HIF1α (t1/2 < 5 min) upon reoxygenation." (PMID 30127847, 2018). "Although both prolyl and asparaginyl hydroxylases represent canonical components of the O2-sensing cell machinery, HIF-1α activation in cancer may rely on additional non-canonical pathways, including several O2-independent molecular mechanisms." (PMID 29996493, 2018). "Therefore, our results support the hypothesis that hypoxia and HIF-1α induction promotes extravasation of MCF-10A and the cancer breast cells." (PMID 30560881, 2018). "Our study, for the first time, suggests the miR-22/IPO7/HIF-1α axis as new molecular target of curcumin, revealing innovative therapeutic implications of this natural compound for treatment of CML as well as of other cancer types in which HIF-1α has a prominent role." (PMID 30045750, 2018).
cancer (continued). "By literature mining we identified some interesting genes (as STAT3, HIF1a, NFKB1, KRAS) that have been reported to play an important role in biological processes as inflammation, EMT, coagulation and angiogenesis, which are at the basis for cancer and cardiovascular diseases." (PMID 29703138, 2018). "Notably, in multiple microarray and RNA-sequencing data sets where LncHIFCAR and HIF-1 target genes are upregulated in the cancer specimens, the levels of HIF1A mRNA are not significantly altered." (PMID 28639619, 2017). "However, the hypoxia-driven HIF-1α upregulation also activates downstream pathways involved in metabolism (e.g. CAIX), angiogenesis (e.g. VEGF/VEGFR2 pathway) and extracellular matrix activity (e.g. LOX), which can modulate cancer behavior." (PMID 28143503, 2017). "The observed decreases in ABC transporters, HIF1α, and TFPIα protein levels, and the enhanced phosphorylation of S6KS473 and p53S392 clearly define a variety of potential pathways that metformin may influence in order to control cancer cell proliferation." (PMID 29211738, 2017). "In respect to cancer, studies have shown that 1,25(OH)2D3 induces the expression of anti-proliferative and pro-apoptotic genes such as p21, p27, and BAX, and decreases the expression of oncogenic transcription factors like MYC and Hypoxia-Inducible factor 1-α (HIF1α)." (PMID 28124999, 2017). "Furthermore, 3D-grown cancer cells showed significantly higher expression of HIF1α, a molecular indicator of hypoxia; the increased expression of VEGF-A in 3D cultured cancer cells was shown to be dependent on the HIF1α activities." (PMID 29200966, 2017). "Given the role of HIF-1α in glucose metabolism and cancer progression, we investigated several levels of HIF-1α regulation in HepG2 cells stimulated with orexin A. Real-time PCR assays demonstrated that the mRNA level of HIF-1α was dose-dependently increased in response to orexin A treatment." (PMID 28886081, 2017). "Altogether these studies suggest that CCL5/CCR5 signaling regulates angiogenic responses in cancer by modulating certain miRNAs, nevertheless the stimulatory actions mediated by CCR5 may also rely on the direct regulation of the HIF-1α/VEGF transduction pathway." (PMID 29240722, 2017). "Among its multiple functions, mTOR may favor cancer metabolic reprogramming by activating HIF-1α even under normoxic conditions." (PMID 29190880, 2017). "Moreover, Mito-CP’s inhibitory effect on hypoxic adaptations in cancer cells (such as aerobic glycolysis mediated by HIF-1α can be correlated with its effects on Akt and H2O2, which are required for synthesis and stabilization of HIF-1α, respectively." (PMID 28426671, 2017). "Nevertheless, HIF-1α-targeting strategies may not be the best way to reverse sorafenib resistance because no HIF-1α inhibitor has been clinically approved to treat cancer." (PMID 27476430, 2016). "Neural progenitor cells display increased proliferation in 10% O2 in an effect mediated by HIF-1α, and the moderate induction of HIF-1α in 5% O2 has been shown to promote proliferation of both cancer and non-cancer cell lines, suggesting an important role in normal cell physiology." (PMID 26966676, 2016). "This lack of expected association between HIF-1α immunoreactive score and ischemia time could be explained by oncogene activation of HIF-1α in cancer." (PMID 27124490, 2016). "The identification of an adaptor molecule containing a methyl recognition domain linking methylated HIF-1α to the E3 ubiquitin ligase complex for degradation would be helpful for understanding methylation-dependent HIF-1α degradation in the nucleus and its biological importance in cancers." (PMID 26757928, 2016).
cancer (continued). "Thus, suppression of HIF-1α by AIM2 may contribute to the restriction and reduction of cancer invasion of these HCC cells." (PMID 27167192, 2016). "Thus, HIF-1α and E2F3 may share common roles in the progression of cancers through the miRNAs identified." (PMID 25714015, 2015). "However, when we analysed the nuclear HIF-1α expression in familial compared to sporadic cancers, we did not observe a substantial difference." (PMID 26312763, 2015). "Alternatively, evidence has shown that induction of angiogenesis by HIF-1α in cancer cells is activated by epidermal growth factor (EGF)/AKT/ERK signaling during hypoxia, and our analysis of miR-622-overexpressing cells revealed decreased HIF-1α-dependent cell invasion." (PMID 26528854, 2015). "On the other hand, activation of PDHC6 can support the energy production in the cancer cells and the effect of GLN could be negative if the apoptosis caused by HIF-1α inhibition did not occur." (PMID 26583064, 2015). "Drinkers showed higher HIF-1α expression in the nucleus of their cancer cells than nondrinkers." (PMID 26695753, 2015). "While we also found HIF1α could be induced after recruited BM-MSCs (with increased CCL5) in PCa cells, we focused on HIF2α here as the recent studies showed that the HIF2α is more important for the cancer stem cell population induction." (PMID 26342197, 2015). "Of the miRNAs putatively interacting with the HIF-1α mRNA, we narrowed our focus to the effect of PPIX on miR-199a-5p because the particular miRNA regulates cancer-related genes and its expression levels decrease in various cancers including liver, colon, breast, bladder, and testicular cancers." (PMID 25714015, 2015). "Indeed we found that SDE-genes identified in previous step are related to STAT3 pathways including genes involved in cell cycle progression (Cyclin D1, D2, and c-Myc), cell survival (Bcl-xL, Bcl-2, Mcl-1), angiogenesis (HIF1α, VEGF), cancer inflammation (NF-KB, IL-6)." (PMID 26056083, 2015). "Moreover, promoter luciferase reporter assays revealed that HIF-1α facilitated transcriptional activation of ILK gene expression in a manner similar to that of hypoxia, confirming that HIF-1α regulates ILK gene expression in hypoxia-exposed cancer cells." (PMID 25821081, 2015). "The following individual cancer metabolism features are very important in analyzing the effect of GLN supplementation: PHDC6 activity, individual TCA enzymes activity profile, malonate concentration, functioning of OXPH chain, oxidative stress, and HIF-1α activity." (PMID 26583064, 2015). "Those agents that only disrupt cellular expression or function of HIF-1α may not possess the ability to kill cancer cells directly." (PMID 26649750, 2015). "It should be noted that the cancer cells treated for 8 weeks in our study, although they no longer expressed HIF1α(PP), did maintain endogenous HIF-1α expression under hypoxia, a potential contributing factor to the process and a disadvantage of our experimental system." (PMID 25893706, 2015). "Furthermore, the roles of HIF-1α and HIF-2α in cancer seem context dependent." (PMID 25893706, 2015). "Admittedly, the results indicate the issue role of GLUTs and interactions with HIF-1α as their key regulator in cancers, but it is not clearly understood and there is a need for future research to clarify the relevance of GLUT proteins in carcinogenicity and the behavior of various tumors." (PMID 25412955, 2015). "However, in cancer cell lines expressing Haps59 the 5FC sensitivity difference between the presence and absence of HIF-1α was not as large as desired." (PMID 25426963, 2014).
cancer (continued). "Moreover, higher mRNA expression of VEGF-A (breast, colon, liver and lung), a HIF-1α-target gene, and select OATPs including OATP2B1 (breast, liver and lung) and OATP4A1 (colon and liver) were seen in canine cancer tissues relative to cancer-adjacent normal tissues as determined by qPCR." (PMID 25361418, 2014). "Under hypoxia, HIF-1α shunts glucose toward glycolysis to maintain cell survival, so we investigated whether PIM2 could augment adaptive responses to hypoxia by increasing glycolysis in cancer cells." (PMID 24505470, 2014). "Indeed, small molecules targeting HIF-1α transcription, translation, and stabilization have been developed, and some of them (e.g., PX-478, Topetican and BAY87-2243) have entered clinical trials for treating cancer patients." (PMID 24925080, 2014). "Therefore, proteins such as HIF-1α and IRE1-XBP1 may be excellent targets in our efforts to treat cancers that have yet to benefit from other targeted therapeutics." (PMID 25927911, 2014). "However, the association between the polymorphisms in HIF1A gene and NSCLC cancer prognosis is not well investigated so far." (PMID 24567056, 2014). "Although a highly structural homology exists between HIF-1α and HIF-2α, these transcription factors may also be differently regulated and transactivate common and unique targeted gene products in a cancer cell-dependent manner under normoxic and hypoxic conditions." (PMID 23301832, 2013). "Unexpectedly, HIF1A stabilization occurred in the absence of tissue hypoxia, and involved normoxic inhibition of SDH, a molecular pathway that has previously been implicated in the normoxic activation of HIF during cancer." (PMID 24086109, 2013). "Other cancer cells were tested to assess whether the inhibitory effects of FCF on HIF-1α are not restricted to PC-3 cells but are rather generalized." (PMID 23977378, 2013). "Furthermore HIF-1α promotes transcription of lactate dehydrogenase (LDH) and lactate monocarboxylate transporters (MCT), and thus plays an important role in the production and efflux of lactate in cancer cells." (PMID 22277092, 2012). "Indeed, HIF-1α is the exclusive regulator of CAIX activity, in contrast to many hypoxia-induced genes, and CAIX is often the most strongly upregulated gene in response to hypoxia in human cancer cells." (PMID 22289741, 2012). "Hypoxia, via HIF-1α-mediated transcription, has been shown to induce an embryonic stem cell-like transcriptional program including pluri-potency-inducing markers like OCT3/4, Nanog, c-Myc, KLF4 and SOX-2 in several cancer cell lines derived from various tissues." (PMID 23185562, 2012). "Moreover, using immunocytochemistry, we further confirmed that HIF-1α was expressed and accumulated in the nuclei of human cancer cells under hypoxic conditions, but not under normoxic conditions." (PMID 22720091, 2012). "Recent studies have suggested that RTK signaling transcriptionally induces HIF-1α while hypoxia enhances RTK signaling via HIF-1-mediated up-regulation of RTKs and the reciprocal relationship between the two distinct oncogenic pathways promotes cancer invasion and angiogenesis." (PMID 24213112, 2011). "The differential expression of hypoxia marker HIF-1α in CD44+CD24-/low tumors is in accordance with the current knowledge regarding relationship between microenvironmental factor such as hypoxia or anoxia states with maintenance and propagation of cancer stem cells." (PMID 21824412, 2011). "We highlight differential expression of STAT3/HIF1 α and C/EBPβ in the CD33+ and CD11b+ subsets, respectively, that may aid other investigators in therapeutic targeting, subset expansion, or MDSC monitoring in cancer patients." (PMID 21658270, 2011). "This implies a possible feedback loop between the glycolytic and HIF-1α pathways that may be critical in the transformation of a normal cell into a cancer cell." (PMID 21320311, 2011).